AR (androgen receptor)
Diseases named in the same sentence as AR in open-access papers (continued):
Sharing a sentence is not in itself a finding about the gene and the disease.
tumor (continued). "It was shown that co-targeting of the PI3K and AR pathway in LNCaP cells resulted in strong anti-tumor effects when compared to single drug treatment." (PMID 34211036, 2021). "All tumours demonstrated high AR immunohistochemical expression, with over 95% of the neoplastic cells showing AR positivity in 19/20 cases." (PMID 33534004, 2021). "Carcinomas with apocrine differentiation (CAD) of the breast are rare tumours typically presenting high immunohistochemical expression of androgen receptor (AR) which is a target molecule for personalised therapy." (PMID 33534004, 2021). "Here, we demonstrated that elevated AR expression was positively correlated with tumor-originated vasculogenesis in ccRCC patients." (PMID 33510354, 2021). "Our transcriptome studies revealed expression of the full-length AR (AR-FL) as well as four of five tested SVs in normal and tumor tissue." (PMID 34440475, 2021). "In line with the general role and mode of action, several miRNAs directly affect or are affected by androgen and androgen receptor (AR) to play a key role in various tumor regulation." (PMID 33499881, 2021). "The importance of heterogeneity of AR expression to the process of tumor adaptation to the androgen environment is addressed further below." (PMID 34575033, 2021). "As such, SPOP plays an unique role in maintaining a steady-state level of AR signaling in prostate epithelial cells and regulating oncogenic transcription, DNA damage repair, and tumor cell migration." (PMID 34795264, 2021). "The recognition that a tumor classified as amphicrine—AR+/NE+—by bulk tumor analysis, actually consisted of distinct subtypes, was readily demonstrated by DSP." (PMID 33658518, 2021). "TRPS1 and SLC2A1 have previously been implicated in PC and AR action, and decreased EFS expression has been associated with more advanced PC and tumor recurrence." (PMID 33974560, 2021). "The MURAL collection contains 33 adenocarcinomas from 19 patients, 18 neuroendocrine tumours from 7 patients, and 8 “mixed” tumours, which have both AR expression and neuroendocrine markers." (PMID 34535657, 2021). "Transcriptome profiling of residual tumours revealed that AR signalling was reduced but continual—a commonality between nADT-resistant and castration-resistant disease." (PMID 35008330, 2021). "JMJD3’s transcriptional level is increased in LNCaP AR+ tumor cell lines compared to PC-3 AR− tumor cell lines." (PMID 33478063, 2021). "Intra-tumour and extra-gonadal androgens are responsible for persistent androgen receptor (AR)-mediated growth in CRPC and are thus considered potential therapeutic targets." (PMID 34381019, 2021). "Targeting EZH2 represents a way of restoring AR signaling in neuroendocrine-differentiated tumor cells." (PMID 35186711, 2021). "In recent years, new compounds have been introduced clinically that target the AR signaling axis resulting in tumor regression." (PMID 34211036, 2021). "Second-line antiandrogen therapy is indicated for the treatment of CRPC patients, supporting the idea that the androgen/AR axis is still active in this progression phase of the tumor." (PMID 34067217, 2021). "It has been reported that AR is positively correlated with pathological tumor staging in HCC patients." (PMID 34907204, 2021). "The AR shows a higher positivity in estrogen receptor alpha-positive (ERα+) luminal A tumours than in triple negative breast cancer (TNBC)." (PMID 35008851, 2021). "At ERC, where tumor growth was halted, AR nuclear expression was significantly lower (P < 0.0001), with heterogeneous nuclear localization and scarce cytoplasmic staining; while ERG reactivity was negative (P < 0.0001)." (PMID 34584218, 2021). "A recent study using the TRAMP C2 CRPC tumor model suggested that the AR signaling pathway regulates the ability of MDSCs to suppress adaptive immunity." (PMID 35011582, 2021).
tumor (continued). "We also confirmed that PLA2G2A, identified as an upregulated gene in the tumor and directly regulated by AR in network #3, to be inhibited by DHT treatments in the cultured LNCaP cells." (PMID 33808801, 2021). "Trials have been approved to evaluate anti-AR therapy efficacy in women affected by AR-positive tumours with promising results." (PMID 33534004, 2021). "Our multi-parameter analysis also demonstrated that ex vivo prostate PDCOs generated from organ-confined tumor tissue maintain AR activity in culture." (PMID 34581895, 2021). "For example, patient 15-096 had one tumor classified as AR+/NE+, whereas a separate metastasis was AR+/NE−." (PMID 33658518, 2021). "Studies herein identify an unexpected, temporally modulated mechanism of DSB repair regulation, mediated by tumor-specific, AR-mediated induction of the CRY1 transcriptional regulator." (PMID 33452241, 2021). "Our analysis revealed a heterogeneous population of CHCs, including those with CD44 and AR expression, which align with the phenotypes detected in both the proliferating tumor compartment and that of tumor hybrids cells." (PMID 34211050, 2021). "The presence of STS, 3β-HSD, and 17β-HSD1 result in the production of testosterone which act through the androgen receptor (AR) in the tumor cell." (PMID 34321053, 2021). "Multiple treatment resistance mechanisms arise from genetic and epigenetic alterations, leading to a rewiring of alternative bypass pathways driving tumor cell growth, but the majority of CRPCs remain AR-dependent through maintenance of AR signaling." (PMID 34283056, 2021). "In univariable analysis, the significant variables were age, HG, NG, tumor subtypes, Ki-67 L.I., androgen receptor (AR) percentage, and continuous SUVmax." (PMID 34103577, 2021). "Reactivation of the androgen receptor (AR) has long been considered a seminal event; supporting renewed tumor growth in a majority of metastatic CRPC patients." (PMID 33585078, 2021). "It is known that alternative pathways (e.g., Wnt and PI3K) are activated to support tumor cell proliferation during the development of the CRPC in response to AR inhibition." (PMID 34439974, 2021). "Several studies show that it promotes PCa initiation and progression by transactivating the androgen receptor, but there are also reports that some subunits function as tumor suppressors." (PMID 34249931, 2021). "KDM4A/C/D bind androgen receptor (AR) in vitro and in vivo, resulting in tumor cell proliferation through demethylation of H3K9me3 in AR target genes, stimulating AR-dependent transcription in combination with KDM1A." (PMID 34778065, 2021). "These TFs act to establish chromatin interactions that regulate a subset of AR target genes important for the promotion of PC tumor growth." (PMID 34283056, 2021). "Multiple mechanisms underlying the CR state, include an increased androgen biosynthesis in the tumor microenvironment, androgen receptor (AR) amplifications and overexpression." (PMID 34631527, 2021). "Over the past decades, preclinical and clinical research on tumor samples from CRPC patients has uncovered diverse resistance mechanisms leading to persistent androgen receptor addiction." (PMID 34073713, 2021). "Upregulated androgenic enzymes within the tumor bulk facilitates enhanced conversion of adrenal steroids into gonadal steroids like testosterone and DHT, with associated AR-mediated transcriptional activation consequently driving castration resistance." (PMID 34298692, 2021). "As to how HAT1 regulates AR expression, there are multiple transcriptional factors, such as MYC, EZH2, TRIM24, KLF4, and BRD4, regulate AR transcription by binding to its promoter in tumor cells." (PMID 34323404, 2021).
tumor (continued). "In addition to the previous theories, other genetic abnormalities could explain the progression of the tumour despite AR blockage; to name a few, the AR gene mutation and/or overexpression, the expression of AR splicing variants, and the upregulation of transcriptional co-activators." (PMID 34768647, 2021). "The results showed that the extracts of AR in different concentrations (2 mg/mL, 4 mg/mL, and 8 mg/mL) had different anti-tumor effects." (PMID 34887934, 2021). "Of note, we previously reported that aR mice exhibited a stronger increase in Tfh cells in tumor- draining lymph nodes (tdLNs) than aNR mice." (PMID 33262469, 2021). "Thus, our data suggest that higher levels of AR mRNA may be associated with BC subtypes reported to be less aggressive and for having better prognosis, which is consistent with recent findings providing evidence that AR has a tumor suppressor role in ER+ BC." (PMID 34571711, 2021). "The conclusions of recently published data suggest that in ER-positive breast cancer, in order to induce and enhance anti-tumor effects, AR agonist should be used and in ER-negative breast cancer, more focus should be put on treatment with ER antagonists." (PMID 33915941, 2021). "Another example of correlation across platforms is given by the high level of AR expression detected by CLIA IHC in both tumor samples from case 1, while ER expression remained low." (PMID 34667258, 2021). "IHC assays proved that the downregulation of LINC00667 weakened the expression levels of AR, Slug and Ki-67 in tumor tissues." (PMID 34907204, 2021). "In a recent paper, Xiao and co-workers furthermore identified the histone lysine-N-methyltransferase EZH2 as a possible epigenetic regulator of tumor response to AR-targeting therapy and demonstrated possibilities with its inhibition in the treatment of CRPC." (PMID 34193246, 2021). "A tumor biopsy was then collected 6 days after the cfDNA sample, and MSK-IMPACT analysis confirmed the presence of this AR mutation at a VAF of 0.3%, significantly below the threshold for de novo mutation calling using the MSK-IMPACT assay." (PMID 34059130, 2021). "The identification of ING1 and ING2 tumor suppressors in the AR-mediated transrepression of hTERT provides some first insights into the link between tumor suppressors and the AR (graphical abstract)." (PMID 34439179, 2021). "Ivermectin significantly reduced AR FL or V7 levels in LNCaP and 22Rv1 cells and xenografts to reduce tumor progression in combination with ARPI." (PMID 33709547, 2021). "Our data reveal that a positive feedback loop between AR and 6PGD enhances growth and survival of tumour cells." (PMID 34382934, 2021). "The androgen receptor (AR) in particular regulates androgen effect on tumor initiation, and behaves an important role in the relapse transition." (PMID 34073059, 2021). "Enhanced splicing of these alternative exons and subsequent translation forms the truncated AR-Vs that can further drive the growth of tumour cells." (PMID 33993099, 2021). "AR plays a pivotal role in prostatic carcinogenesis, and AR related signaling pathways retain the tumor characteristics of HSPC." (PMID 33708629, 2021). "Taken together, miR-299-3p exerts anti-tumor effects via affecting activity of AR and VEGFA pathways." (PMID 34831421, 2021). "We also report here that p38 activity is further exacerbated by hypoxia in CRPC cells, and drives Hsp27 activation, AR signaling, cell proliferation, cell survival and tumor growth (see graphical abstract)." (PMID 33671134, 2021). "mRNA from 76 R/M androgen receptor (AR)-positive SDC patients treated with leuprorelin acetate combined with bicalutamide was extracted from pre-treatment tumor specimens." (PMID 34298742, 2021). "Epigenetic alterations during PC progression remain elusive and this study aims to explore promoter gene methylation signatures in relation to gene expression and tumor AR activity." (PMID 34193246, 2021).
tumor (continued). "PIP5K1α, pAKT and AR was also highly expressed in primary tumor tissues and metastatic lesions from PCa patients in these cohorts." (PMID 33275817, 2021). "That said, we observed after GSK126 co-treatment a continuous relative increase in tumor cell numbers of cluster h6—the least progressed cluster on the trajectory that also displayed the highest AR mRNA levels." (PMID 34857732, 2021). "The relapse, or re-progression, of the tumor, usually via adaptive responses, relies on activated alternative pathways besides AR signaling." (PMID 34681745, 2021). "Tumor growth and disease progression is mainly dependent on the Androgen Receptor (AR), a ligand dependent transcription factor." (PMID 33972681, 2021). "The effects of AR signalling have been observed in the clinic, where ER+/AR+ tumours are typically smaller, well differentiated, and a prognostic factor for longer disease-free survival." (PMID 33671468, 2021). "Patient 12-011 had one tumor classified as AR+/NE− and one tumor AR+/NE+ and patient 15-010 had one tumor classified as ARlow/NE− and one tumor AR−/NE+." (PMID 33658518, 2021). "MIIP inhibition of miRNA 181a-5p and 181b-5p also leads to reduced expression of SNAIL and TWIST, and knockdown of MIIP promoted tumor growth or osteolytic bone lesions, as well as AR activity." (PMID 33672595, 2021). "In both GEMM and ODT models, tumour cells in the metastatic foci displayed expression of Hoxb13, low levels of AR and K8 but high levels of Syp and Ncam, suggesting the prostatic origin and stable neuroendocrine signature of these metastatic tumour foci." (PMID 34021647, 2021). "During PC progression, tumor cells become androgen-independent and the AR inhibition of human prostate cells promotes cell migration and invasiveness." (PMID 33920045, 2021). "For example, many genes involved in the modulation of the androgen receptor function were inhibited in the LNCaP xenograft tumor, including Hsp90AA2P, FLNA, and FKBP4." (PMID 33808801, 2021). "The majority of both male and female GBMs were found to have high AR nuclear expression levels in a significant percentage of cells in tumor." (PMID 34094902, 2021). "Differential expression analysis revealed lower expression of genes in metabolic pathways, mTOR, MYC, and AR pathways in the Castrated group compared to the Intact tumor groups." (PMID 33602919, 2021). "When PCa progresses to CRPC, enzalutamide or abiraterone (new endocrine therapy [NET]) was used as a clinical treatment to further inhibit AR pathway, but the tumor still cannot be cured eventually." (PMID 34185414, 2021). "Mass-spectrometric-based studies of the AR have been restricted to quantifying androgens in tumor tissue, confirming AR sequences, identifying AR phosphorylation sites, identifying AR-binding partners, and establishing evidence for AR dimerization." (PMID 33384381, 2021). "The paradoxical tumor-suppressive effects induced by the relatively high AR expression in PC3 and DU145 cells are reminiscent of the antitumor responses triggered by supraphysiologic androgen levels in recent clinical studies." (PMID 33420371, 2021). "Our results showed that AR mRNA levels were higher in tumor tissues from patients classified as Luminal A, Luminal B, HER2-enriched, and Normal-like subtypes, when each one of them was compared to tissues from Basal-like cases (p < 0.001)." (PMID 34571711, 2021). "AR in orthotopically growing tumor cells showed variable staining intensities and nuclear-dominant expression patterns but was also detectable in cytosol." (PMID 34094902, 2021). "It has similar preclinical activity to ARV-110 in regards to effective AR protein degradation, favorable pharmacokinetic properties, and sustained suppression of tumor growth in VCAP CRPC mouse models." (PMID 36046114, 2021). "Mechanistically, PART1 acts as a role of tumor suppressor by interacting with androgen receptor (AR) and stimulating the PLZF gene expression in GC cells." (PMID 35155211, 2021).
tumor (continued). "The results confirmed that BIC decreased the AR expression and inhibited tumor proliferation in both female host mice." (PMID 33947843, 2021). "Clinical research further demonstrated that if tumor cells of patients with CRPC positively expressed AR-v7, these patients would be resistant to ENZ treatment." (PMID 34746227, 2021). "In our study, CD20 was expressed in 90.3% of the tumours and its median expression was significantly higher in AR− versus AR+ TNBC (20% versus 7.5%, respectively, p = 0.008)." (PMID 35047068, 2021). "For two tumors, the tumor phenotype classification diverged across ROIs, with one tumor having ROIs with both AR+/NE− and ARlow/NE− regions (12-005K1) and one tumor having ROIs with both ARlow/NE− and AR−/NE− phenotypes (15-010K2)." (PMID 33658518, 2021). "Three sex hormone receptors (AR, ER, and PR) in Subtype-B tumor patients were higher than in Subtype-A tumor patients in GC, while the HER2 displayed an opposite trend." (PMID 34977116, 2021). "All tumours showed AR protein expression on immunohistochemistry, with greater than 95% of the neoplastic population staining positively in 19/20 cases." (PMID 33534004, 2021). "The inhibition of BRD4 reduces the levels of AR-driven target genes in PC, decreasing tumor burden in murine models." (PMID 34830196, 2021). "In hormone-dependent PCa and BC, the AR and ER function as transcription factors to regulate genes involved in cell cycle progression, metabolism, and other cellular functions to promote tumor growth." (PMID 34201346, 2021). "Emerging evidence indicates that the menin–MLL complex is upregulated in PCa, plays a role in AR signaling in AR-positive tumors, and can be targeted with small molecule inhibitors to reduce xenograft tumor growth." (PMID 34685704, 2021). "Given the overall downregulation of AR-mediated pathway in tumor, we consider the main regulator of CXCR7 in the xenograft tumor is inflammation." (PMID 33808801, 2021). "The large number of non-responders also argues for the presence of intrinsic ADT resistance mechanisms, such as active tumor-driving signal transduction pathways other than AR signaling, which has yet to be explored." (PMID 34298742, 2021). "In these tumors, RPPA as well as Cyc-IF analysis demonstrated that the hormone signaling pathway was activated, supporting the AR as a contributor to tumor biology in this patient." (PMID 34667258, 2021). "Substantial heterogeneity of AR expression from cell to cell was observed in the overexpressing tumor." (PMID 34575033, 2021). "It interferes with androgen receptor (AR) functions, keeping tumor progression in pace only for few months before recurrence." (PMID 34356101, 2021). "Race, lymph node involvement, tumor size, androgen receptor, tumor grade and age at diagnose seem to be prognostic factors in MBC." (PMID 33964913, 2021). "Our analyses indicate a downregulation of AR expression and an overall inhibition of AR-mediated pathways in the tumor samples vs. culture cells." (PMID 33808801, 2021). "There are multiple transcriptional factors, such as MYC, EZH2, TRIM24, KLF4, and BRD4, that can regulate AR transcription by binding to its promoter in tumor cells." (PMID 34323404, 2021). "Our study showed that 49% of the pan-CK-positive objects were EpCAM-negative, of which the majority expressed other tumor markers in addition to pan-CK, including AR, PSA and PSMA." (PMID 33801459, 2021). "Significant reduction of AR protein expression has been observed in paired tumor specimens by immunohistochemistry before and after 6 weeks of treatment with ARV-110 at 280 mg." (PMID 36046114, 2021). "Conversely, when PgR is lost, another receptor, ERβ, down-regulates ERα target genes, whereas AR enhances ERα target gene transcription and potentially contributes to tumor growth." (PMID 34638241, 2021).